HSP90AA1 (heat shock protein 90 alpha family class A member 1)
Diseases named in the same sentence as HSP90AA1 in open-access papers (continued):
Sharing a sentence is not in itself a finding about the gene and the disease.
gliosarcoma (1 paper, 2013). A rare histological variant of glioblastoma (WHO grade IV) characterized by a biphasic tissue pattern with alternating areas displaying glial and mesenchymal differentiation (WHO). "It is not surprising in light of higher inducible potential of Hsp90AA1 as observed in the rat 9L gliosarcoma cells." (PMID 24015183, 2013).
hyperlipidemia (1 paper, 2024). "The estrogen signaling pathway was regulated by CA binding to HSP90AA1, MMP2, RARA, PRKACA, ESR1, MMP9, and ESR2 in this present research, which underlies the improvements observed in hyperlipidemia and thrombosis." (PMID 38398534, 2024).
Inguinal hernia (1 paper, 2020). Protrusion of the contents of the abdominal cavity through the inguinal canal. "We discovered that PIK3R1, PTPN11, TGFBR1, CDC42, SOS1, and KRAS were the most essential inguinal hernia-causative proteins and UBC, GRB2, CTNNB1, HSP90AA1, CBL, PLCG1, and CRK were listed as the most commonly-involved downstream proteins." (PMID 31910207, 2020).
ischemia reperfusion injury (1 paper, 2025). Adverse functional, metabolic, or structural changes in ischemic tissues resulting from the restoration of blood flow to the tissue (reperfusion), including swelling; hemorrhage; necrosis; and damage from free radicals. "Experimental evidence indicates that HSP90AA1 (Heat Shock Protein 90α subtype), an ATP-dependent molecular chaperone, participates in the cascade reactions of ischemia-reperfusion injury by modulating conformational changes of transcription factors such as NF-κB and HIF-1α." (PMID 40808948, 2025).
kidney cancer (1 paper, 2023). Primary or metastatic malignant neoplasm involving the kidney. "PIK3CA, IL1R1, HSP90AA1, and ATG5 were significantly lower expressed in tumor tissues (p < 0.05), which were further confirmed by the protein expression profile in kidney cancer downloaded from HPA database." (PMID 36932108, 2023).
laryngeal carcinoma (1 paper, 2018). Carcinoma that arises from the laryngeal epithelium. "We choose cutoff 1200 for degree and therefore YWHAZ and PPP2R1A as the toptwo up-regulated genes and also HSP90AA1 and CALM3 as the top two down-regulated genes areintroduced as human laryngeal cancer." (PMID 29755572, 2018). "Among 275 investigated proteins, 12 crucial proteinsare determined that 4 of them can be introduce as a possible biomarker panel includingYWHAZ, PPP2R1A, HSP90AA1, and CALM3 for human laryngeal cancer." (PMID 29755572, 2018). "Finally, a possible biomarker panelincluding YWHAZ and PPP2R1A as the two up-regulated genes and HSP90AA1 and CALM3 as the twodown-regulated genes for human laryngeal cancer is introduced." (PMID 29755572, 2018).
metastatic tumors (1 paper, 2021). "It suggests that targeting the common gained enhancer-linked oncogenic targets in primary and metastatic tumors, such as HSP90AA1, is a potential strategy for ESCC therapy." (PMID 34294701, 2021).
muscle atrophy (1 paper, 2023). The loss of muscle tissue due to inactivity or disease. "Our molecular docking results showed that Aloin A had good binding interactions with HSP90AA1, AKT1, CTNNB1, BCL2L1, RELA, TNF, AKT3, the ranging from −7.9 to −8.9 kcal/mol, suggesting that Aloin A stably combined with these proteins for attenuating cancer related muscle atrophy." (PMID 38180061, 2023).
Neurodegeneration (1 paper, 2013). Progressive loss of neural cells and tissue. "The compact shortest path network included many noteworthy connecting proteins like APP, CREB1, HSP90AA1, MAPT and PTEN which were previously implicated to play critical roles in many neurodegeneration disease pathogenesis and couple of them were indicated to have neuroprotective mechanism." (PMID 24688734, 2013).
oral squamous cell carcinoma (1 paper, 2022). "Another study showed that miR-27a transfection led to decreased HSP90AA1 gene expression levels in human oral squamous cell carcinoma (HSC-4) cells under stress conditions but not under normal growth conditions." (PMID 36497000, 2022).
ovarian endometriosis (1 paper, 2010). A non-neoplastic disorder characterized by the growth of endometrial tissue in the ovaries. "Hsp90aa1 expression is up-regulated in ovarian endometriosis while P4hb is involved in post-translational modifications of procollagen synthesis." (PMID 21210965, 2010).
ovarian tumor (1 paper, 2024). "RT-qPCR results showed that SOD1 exhibited consistent expression with HSP90AA1 and HSPA8, while SREBF2 and GTAT2 were highly expressed in non-malignant ovarian tumor tissues and significantly decreased in high-grade serous ovarian cancer samples." (PMID 38166541, 2024). "The IHC and RT-qPCR results revealed that HSP90AA1 and HSPA8 were downregulated in non-malignant ovarian tumor tissues and significantly upregulated in high-grade serous ovarian cancer samples." (PMID 38166541, 2024).
pancreatic adenocarcinoma (1 paper, 2019). "The canonical chaperone Hsp90 isoforms HSP90AA1 and HSP90AB1 were also found to be upregulated in several cancers including pancreatic adenocarcinoma, thymoma, and prostate adenocarcinoma, respectively." (PMID 31814876, 2019).
Peri-Implantitis (1 paper, 2022). An inflammatory process with loss of supporting bone in the tissues surrounding functioning DENTAL IMPLANTS. "This study will further explore the role of HSP90AA1 gene in the development of peri-implantitis, and provide a potential target for clinical treatment of peri-implantitis." (PMID 36028869, 2022). "This will provide a theoretical basis for us to explore the mechanism of HSP90AA1 involving in peri-implantitis." (PMID 36028869, 2022). "It suggested that HSP90AA1 promoted the inflammatory response of Pg-LPS induced HGFs by regulating autophagy, indicating that HSP90AA1 played an important role in peri-implantitis, and might provide a potential therapeutic target for clinical treatment." (PMID 36028869, 2022). "This study aimed to investigate the role of HSP90AA1 in the inflammatory of human gingival fibroblasts (HGFs) induced by porphyromonas gingivalis lipopolysaccharide (Pg-LPS), and to provide a potential therapeutic target for clinical treatment of peri-implantitis." (PMID 36028869, 2022). "Our previous study found that HSP90AA1 might be a key gene in the development of peri-implantitis." (PMID 36028869, 2022).
polyp (1 paper, 2021). A usually exophytic mass attached to the underlying tissue by a broad base or a thin stalk. "In case of polyp type, the HSP90AA1 expression rate increasing along with growing contribution of villous growth pattern resulted not from both decreasing gene expression in adjacent tissue and from increasing expression in polyp." (PMID 34827586, 2021).
prostate adenocarcinoma (1 paper, 2023). "HSP90AA1 gene expression was negatively correlated with the gene expression of MZF1(ZSCAN6), SCAND1, SCAND2, and HSF4 in prostate adenocarcinoma specimens." (PMID 36982267, 2023). "To ask whether HSP90AA1 gene was regulated by transcription factors, including SCAN-TFs and HSFs, we examined their co-expression correlation in prostate adenocarcinoma specimens." (PMID 36982267, 2023). "HSP90AA1 gene expression was not significantly correlated with the gene expression of HSF1, HSF2, and HSF5 in prostate adenocarcinoma specimens." (PMID 36982267, 2023).
prostate tumor (1 paper, 2022). "Though normal prostate tissues show no HSP90AA1 expression, in prostate tumor tissues, the gene is weakly expressed or not expressed." (PMID 35594510, 2022).
rectal polyps (1 paper, 2021). "It was associated with a tendency towards higher HSP90AA1 expression in rectal polyps accompanied by lower expression in rectal polyp-adjacent mucosa." (PMID 34827586, 2021).
sarcoma (1 paper, 2014). A usually aggressive malignant neoplasm of the soft tissue or bone. "PIM1 is a client protein of HSP90AA1 in oncogenesis, and plays important roles in sarcoma growth and bone invasion." (PMID 25167922, 2014). "Consistent with this hypothesis, PIM1 (a client protein of HSP90AA1 that affects sarcoma growth and bone invasion) is rapidly decreased in the 2-24a/Cu-treated cells." (PMID 25167922, 2014).
SARS-CoV infections (1 paper, 2022). "It was found that 45.87% of the associated genes (CASP3, CASP9, MAPK1, MAPK3, XIAP) contributed to cytochrome C-mediated apoptotic response and 3.67% of the associated genes (BECN1, FXYD2, GSK3B, HSP90AA1, ITGB1, MAP1LC3B) contributed to SARS-CoV infections." (PMID 36164436, 2022).
schizophrenia (1 paper, 2025). A major psychotic disorder characterized by abnormalities in the perception or expression of reality. "In this study, we investigated the association between the polymorphisms of the HSP90AA1 gene and the risk of developing schizophrenia and the clinical features of the disease in a Polish Caucasian population." (PMID 41010037, 2025). "It is worth mentioning that HSP90AA1 is in the SZDB database, which contains the schizophrenia risk genes that have been identified using different methods." (PMID 41010037, 2025).
scrapie (1 paper, 2011). A fatal disease of the nervous system in sheep and goats, characterized by pruritus, debility, and locomotor incoordination. "Only recently, HSP90AA1 has been analysed as a possible candidate gene involved in scrapie susceptibility in sheep, probably by modulating the incubation period of this disease." (PMID 21314976, 2011). "An association analysis established differential distribution of certain polymorphisms in the 5' and 3' regions of the ovine HSP90AA1 gene in scrapie-susceptible animals." (PMID 21314976, 2011).
seminoma (1 paper, 2025). A radiosensitive malignant germ cell tumor found in the testis (especially undescended), and extragonadal sites (anterior mediastinum and pineal gland).
Stroke (1 paper, 2025). Sudden impairment of blood flow to a part of the brain due to occlusion or rupture of an artery to the brain. "Four hub PANRGs (MCL1, TNFRSF1A, STAT3, Hsp90aa1) were identified, enriched in MAPK and PI3K-AKT signaling pathways and negatively associated with oxidative phosphorylation, suggesting their involvement in stroke pathogenesis." (PMID 41235394, 2025).
teratoma (1 paper, 2025). A non-seminomatous germ cell tumor characterized by the presence of various tissues which correspond to the different germinal layers (endoderm, mesoderm, and ectoderm). "Similarly, the miRNA regulatory network associated with teratoma hub genes demonstrates distinct miRNA clusters targeting essential oncogenic regulators such as CDK1, HSP90AA1, HSPA4, TRIM28, and TOP2A." (PMID 40869426, 2025). "Conversely, the teratoma network was dominated by CDK1, HSP90AA1, TRIM28, and TOP2A—genes critically involved in mitotic progression, chromatin remodeling, and cellular stress response." (PMID 40869426, 2025).
vascular dementia (1 paper, 2025). A degenerative vascular disorder affecting the brain. "Based on these results, HSP90AA1, HSPA1B, and DNAJB1 show considerable potential as diagnostic and therapeutic targets for vascular dementia, offering crucial molecular-level support for clinical diagnosis and subsequent treatment strategy formulation in VaD." (PMID 40808948, 2025). "This study, through the integration of multi-omics data and cross-validation with machine learning algorithms, systematically elucidates the pivotal regulatory roles and diagnostic value of heat shock protein family members HSP90AA1, HSPA1B, and DNAJB1 in vascular dementia (VaD)." (PMID 40808948, 2025). "This study integrates multi-omics data and machine learning to elucidate the immune-neurovascular regulatory roles of HSP90AA1, HSPA1B, and DNAJB1 in vascular dementia (VaD), supporting the core hypothesis that protein homeostasis imbalance drives VaD-related neuroinflammation." (PMID 40808948, 2025).
Wilms tumor (1 paper, 2023). An embryonal neoplasm characterized by the presence of epithelial, mesenchymal, and blastema components. "We found that core genes (CCT4, HSP90AA1, NCL, PABPC1, YBX1) were lowly expressed in tumor tissue samples and highly expressed in standard tissue samples, which may have reverse regulatory significance for Wilms tumor." (PMID 37058032, 2023).
cancer (183 papers, 2008 to 2026). A tumor composed of atypical neoplastic, often pleomorphic cells that invade other tissues. "Pathway analysis using GO, KEGG, and Reactome further narrowed down potential molecular targets, showing notable associations with apoptosis signaling pathways in cancer, particularly for HSP90AA1, MAPK1, and PIK3CA." (PMID 39518920, 2024). "Given the physiological roles of these client proteins, HSP90AA1 is closely linked to various diseases (e.g., cancer, neurodegenerative diseases)." (PMID 39857345, 2024). "HSP90AA1, a member of the molecular chaperone network, is upregulated in response to cellular stress and has been implicated in cancer aggressiveness and poor survival outcomes in various cancers." (PMID 39518920, 2024). "In cancer cells, HSP90AA1 encoded protein can form complexes with various tumor-associated proteins and participate in regulating their stability and activity." (PMID 37587188, 2023). "Concerning the ELOVL1, UGDH and HSP90AA1, studies only showed the correlation with cancer, and further exploration is needed to elucidate the underlying mechanisms." (PMID 36632140, 2023). "The 90-kDa heat shock protein HSP90AA1 is a chaperone protein associated with numerous client proteins that are highly expressed in many cancer cells." (PMID 25167922, 2014). "Moreover, HSP90AA1 shows significant associations with immune checkpoint genes in pan-cancer analyses." (PMID 40141751, 2025). "Indeed, the upregulation of HSP90AA1 was associated with the occurrence, invasion, metastasis, and progression of various malignant tumors." (PMID 37547757, 2023). "However, overexpression of HSP90AA1 in multiple cancers was associated with tumorigenesis and development, making it a potential target for cancer therapy." (PMID 35590292, 2022). "HSP90AA1 is a ubiquitously expressed molecular chaperone that is involved in the stability of mutated and overexpressed signaling proteins that promote the survival of cancer cells." (PMID 30153855, 2018). "Secretion of HSP90AA1 was implicated in increased cell mobility and cancer invasiveness." (PMID 28468249, 2017). "One of the possible reasons is that whole-genome sequencing of all tumor types and cancer cell lines revealed 115 different mutations in HSP90AA1 open reading frame, which may lead to the failure of HSPAA1 transcription in tumors and reduce the degree of malignancy of tumors." (PMID 36158677, 2022). "The top cancer genes with recurrent variants included: STAT2 (33%), DMNT1 (27%), HSP90AA1 (17%), CDK4, NOTCH2, THRAP3, and SALL4 (13% each)." (PMID 41353477, 2025). "MA exerts its anticancer effects by targeting key proteins such as EGFR, SRC, HSP90AA1, MDM2, and IGF1R, which are often overexpressed or mutated in resistant cancer cells." (PMID 40070571, 2025). "Differential expression analysis revealed that HSP90AA1 varied across subclusters in most cancers, while the largest number of ICD-related genes showed subgroup differences in BLCA and THYM." (PMID 41150760, 2025). "HSP90AA1 aids antigen release from cancer cells in TIME, while EZH2, STAT1, and ICAM1 hinder immune cell infiltration." (PMID 40352921, 2025). "It is important to clarify that not all of these proteins act exclusively as tumor suppressors; some, such as EGFR, STAT3, SRC, and HSP90AA1, are oncogenic drivers whose inhibition can suppress cancer growth." (PMID 41150809, 2025). "HSP90AA1 is a heat shock protein that is closely related to the occurrence and development of a variety of cancers." (PMID 41204487, 2025). "The results demonstrated that HSP90AA1 was enriched in cancer pathways such as the Hippo pathway, PLK1 pathway, PI3K/AKT pathway and WNT pathway." (PMID 39567496, 2024). "These animal models allow researchers to study the effects of HSP90AA1 inhibition on tumor growth, metastasis, and response to treatment, providing essential data for the development of novel cancer therapies." (PMID 38785796, 2024).